ZBP1 (Z-DNA binding protein 1)
Diseases named in the same sentence as ZBP1 in open-access papers (continued):
Sharing a sentence is not in itself a finding about the gene and the disease.
fungal infection (4 papers, 2020 to 2022). "To understand the contribution of ZBP1 to PANoptosis during fungal infections, we infected BMDMs from WT and ZBP1-deficient mice with C. albicans or A. fumigatus." (PMID 33109609, 2020). "The residual activation we observed in ZBP1/RIPK3-deficient BMDMs in this study suggests that there could be additional pathways or PANoptosome components such as RIPK1 that are functioning during fungal infection." (PMID 33109609, 2020). "Innate immune sensor Z-DNA binding protein 1 (ZBP1) is the apical sensor of fungal infection and controls the NLRP3 inflammasome to participate in pyroptosis." (PMID 36311726, 2022). "Compared to wild-type BMDMs, ZBP1−/− or ZBP1ΔZα2 BMDMs show significantly attenuated PANoptosis and the release of IL-18 after fungi infection." (PMID 36142136, 2022). "Overall, our results suggest that the Zα2 domain of ZBP1 is critical to trigger PANoptosis during fungal infection." (PMID 33109609, 2020). "Given the clear role for ZBP1 in C. albicans- or A. fumigatus-mediated inflammasome activation and PANoptosis, we assessed the release of the inflammatory cytokine IL-18 after fungal infection." (PMID 33109609, 2020). "Further, we identified the innate immune sensor Z-DNA binding protein 1 (ZBP1) as the apical sensor of fungal infection responsible for activating the inflammasome/pyroptosis, apoptosis, and necroptosis." (PMID 33109609, 2020). "Our study is the first to shed light on the role of ZBP1 in inflammasome activation and PANoptosis during fungal infection, and there are several interesting questions that remain to be addressed." (PMID 33109609, 2020). "Upon Aspergillus fumigatus or Candida albicans infection, mouse and human macrophages activate inflammasome and undergo PANoptosis (pyroptosis, apoptosis, and necroptosis) via a mechanism that requires the innate immune sensor Z-DNA binding protein 1 (ZBP1) as an apical sensor of fungal infection." (PMID 35844522, 2022). "While it is not clear how ZBP1 is activated during fungal infection, it is expected that ZBP1-mediated PANoptosis may be important in controlling fungi infection via the inflammatory response." (PMID 36142136, 2022).
HCMV infection (4 papers, 2014 to 2024). "In the context of human cytomegalovirus (HCMV) infection, ZBP1 amplifies HCMV-induced IRF3 activation and IFN-β expression." (PMID 38402193, 2024). "In the context of HCMV infection, ZBP1 enhances HCMV-induced IRF3 activation and IFN-β expression." (PMID 38402193, 2024). "Moreover, DDX3 contributes the DNA sensor ZBP1/DAI-dependent IFN response after human cytomegalovirus infection." (PMID 25538732, 2014).
hepatocellular carcinoma (4 papers, 2021 to 2024). A malignant tumor that arises from hepatocytes. "In this study, we constructed a scoring model (VM Score) associated with VM, which included three risk factors, SPP1, ADAMTS5, and ZBP1, revealing potential prognostic biomarkers for hepatocellular carcinoma." (PMID 39748947, 2024). "This demonstrated that all three receptor pathways were inducible in the hepatoma cells, and that the upregulated expression of receptors, adaptor molecules, and effector cytokines after 24 hours, especially of ZBP1/DAI and AIM2, was fairly comparable to those obtained in PWHs." (PMID 34671360, 2021). "Hepatitis B virus (HBV) relies on ZBP1-mediated necroptosis during the progression from chronic HBV infection (CHI) to HBV-related hepatic fibrosis (HBV-HF) and HBV-related hepatocellular carcinoma (HBV-HCC)." (PMID 39614405, 2024). "IMP1 is also known as the zipcode binding protein (ZBP1), whereas an alternative splice product of IMP2 is aberrantly expressed in human hepatocellular carcinoma and therefore identified as HCC or auto-antigen p62." (PMID 34685634, 2021). "For confirming the presence of IFI16, ZBP1/DAI, and AIM2 in hepatocytes rather than in immune cells possibly contaminating the PWH cultures, woodchuck WCH-17 hepatoma cells were treated with HSV-60 and poly(dA:dT)." (PMID 34671360, 2021).
inflammatory bowel disease (4 papers, 2020 to 2025). A spectrum of small and large bowel inflammatory diseases of unknown etiology. "Deletion or mutation of Zα residues in ZBP1 confirm a central role for the Z-conformation in RIPK3-dependent necroptosis that occurs in inflammatory bowel disease (IBD), dermatitis and influenza virus infection." (PMID 32742689, 2020). "Given the critical role of ZBP1 as a pathogen sensor and a regulator of cell death and inflammation, ZBP1 is also involved in several diseases, such as infection, skin inflammation, and inflammatory bowel disease." (PMID 39026271, 2024). "The Zα and RHIM1 domains-dependent ZBP1 sense the viral dsRNA to induce necroptosis in IECs, which inevitably destroys the homeostasis of the epithelial barrier and causes inflammatory bowel disease (IBD)." (PMID 36142136, 2022). "Activation of ZBP1 by endogenous retroviruses (ERV) is also reported in human inflammatory bowel disease (IBD) patients, possibly due to low expression levels of the repressive methyltransferase SETDB1." (PMID 32742689, 2020). "IRF1 upregulates multiple PANoptosome components, including ZBP1, RIPK1, and AIM2, driving PANoptosis in models of inflammatory bowel disease (IBD) and alcoholic liver disease." (PMID 41583472, 2025).
periodontitis (4 papers, 2021 to 2025). An acute or chronic inflammatory process that affects the tissues that surround and support the teeth. "In this study, we propose a novel pathogenic model of P. gingivalis-induced periodontitis, suggesting that P. gingivalis activates Zbp1-mediated PANoptosis in macrophages, thereby contributing to periodontal tissues damage." (PMID 40307566, 2025). "This study preliminarily demonstrates the diagnostic potential of ZBP1 in periodontitis and its possible involvement in PANoptosis; however, several limitations remain." (PMID 40612110, 2025). "Currently, research on ZBP1 as a diagnostic biomarker for periodontitis is limited." (PMID 40612110, 2025). "RT-qPCR validation demonstrated that ZBP1 expression was significantly elevated in periodontitis tissues compared to healthy periodontal tissues (P < 0.05)." (PMID 40612110, 2025). "Collectively, these limitations highlight the necessity of integrating mechanistic investigations, technological advancements, and clinical validation to comprehensively elucidate the functional network and translational prospects of ZBP1 in periodontitis." (PMID 40612110, 2025). "The results showed that ZBP1 expression was significantly higher in periodontitis tissues than in healthy gingival tissues (P < 0.01)." (PMID 40612110, 2025). "The intersection of these three machine learning approaches revealed six potential biomarkers associated with PANoptosis in periodontitis: PECAM1, CXCR4, SELP, IL2RG, CD48, and ZBP1." (PMID 40612110, 2025). "Through comprehensive bioinformatics analysis and literature review, ZBP1 was identified as a PANoptosis-related biomarker in periodontitis." (PMID 40612110, 2025). "Based on a ligature-induced mouse model of periodontitis, P. gingivalis was injected vertically into the alveolar crest of WT and Zbp1−/− mice." (PMID 40307566, 2025). "ZBP1, in particular, is closely related to PANoptosis and was thus selected as a potential biomarker in periodontitis." (PMID 40612110, 2025). "To analyze how the Zbp1 functions when periodontal tissue is repaired, we utilized a ligature induced periodontitis model where the periodontal tissue is damaged upon a ligature placement but repaired after the removal of the ligature." (PMID 33824390, 2021). "In conclusion, Sal B@MNs and other drugs targeting Zbp1 and the downstream regulatory mechanism of PANoptosis may represent new strategies for alleviating periodontal tissue destruction and treating periodontitis." (PMID 40307566, 2025). "Due to the good diagnostic ability of ZBP1 and its correlation with immune cells, ZBP1 may serve as a non-invasive biomarker detectable in salivary or crevicular fluid assays for the early screening and monitoring of periodontitis." (PMID 40612110, 2025). "In a mouse model of periodontitis, daily intraperitoneal administration of Stat3 (5 mg/kg) and Stat5 (5 mg/kg) inhibitors significantly reduced P. gingivalis-induced periodontal resorption and Zbp1 induction." (PMID 40307566, 2025). "ZBP1 was identified as a key PANoptosis-related biomarker, suggesting that periodontitis may involve activation of the ZBP1-mediated PANoptosome complex." (PMID 40612110, 2025). "Collectively, our results highlight the crucial role of Zbp1-mediated PANoptosis in periodontitis." (PMID 40307566, 2025). "The potential of Zbp1 as a therapeutic target for alleviating P. gingivalis-induced macrophage death and periodontal resorption has also been explored, suggesting a theoretical basis for novel targeted tissue regeneration strategies in periodontitis." (PMID 40307566, 2025). "Researchers concluded that targeting Zbp1 could be a potential strategy to reduce tissue damage in periodontitis." (PMID 40307566, 2025).
periodontitis (continued). "RT-qPCR validation using clinical gingival tissue samples confirmed that ZBP1 expression was significantly higher in periodontitis samples than in healthy controls (P < 0.01), suggesting its involvement in disease pathogenesis and highlighting its potential diagnostic value (AUC >0.80)." (PMID 40612110, 2025). "Therefore, ZBP1 was identified as a PANoptosis-related biomarker in periodontitis." (PMID 40612110, 2025). "Furthermore, rank-sum test analysis in this study revealed differential expression of key PANoptosome components such as RIPK3, CASP8, and CASP1, suggesting that periodontitis may involve ZBP1-mediated PANoptosome formation." (PMID 40612110, 2025). "Analyses of gingival tissues from healthy and periodontitis individuals demonstrated a statistically significant increase in the expressions of IL-1β, TNF-α and ZBP1 in infected tissues." (PMID 40307566, 2025). "The machine-learning method, RF, was performed to create an ideal model to predict the occurrence of periodontitis and selected five hub PRGs (CHMP2B, GZMB, ZBP1, IL1B, and IRF1)." (PMID 37090158, 2023). "Furthermore, as a core regulator of PANoptosis, ZBP1 represents a potential therapeutic target; small molecule inhibitors or pathway-specific modulators could be designed to suppress aberrant inflammatory cell death and immune cell recruitment in periodontitis." (PMID 40612110, 2025). "In addition, ZBP1 can form a ZBP1-NLRP3 inflammasome complex to mediate caspase-1 activation and IL-1β maturation, suggesting that inflammatory vesicle signalling and PANoptosis may co-exist in the pathological process of periodontitis." (PMID 40612110, 2025).
skin inflammation (4 papers, 2024 to 2025). "Here we show that ZBP1 causes skin inflammation by inducing RIPK3-mediated necroptosis and RIPK1-caspase-8-mediated apoptosis in keratinocytes." (PMID 38849574, 2024). "Moreover, transgenic expression of C-terminally truncated constitutively active ZBP1 (ZBP1ca) in mouse epidermis caused skin inflammation that was only partially inhibited by abrogation of RIPK3-MLKL-dependent necroptosis and fully prevented by combined deficiency in MLKL and caspase-8." (PMID 38849574, 2024). "Genetically, we reveal a functional overlap between STING and ZBP1 as drivers of lethal dermatitis independently of tumour necrosis factor receptor 1 (TNFR1), identifying an aetiology of necroptotic inflammation." (PMID 40834903, 2025). "Histological examination of skin sections showed suppression of lethal dermatitis as evidenced by normalized epidermal thickness, loss of p-MLKL and ZBP1 expression and CD45+, and Cl-CASP3-positive cells." (PMID 40834903, 2025). "ZBP1 induced TNFR1-independent skin inflammation in mice with epidermis-specific ablation of FADD by triggering keratinocyte necroptosis." (PMID 38849574, 2024). "Here we show that combined ablation of TNFR1 and ZBP1 fully prevented skin inflammation in FADDE-KO mice, demonstrating that ZBP1-mediated necroptosis drives TNFR1-independent skin inflammation upon keratinocyte-specific inhibition of FADD/caspase-8 signaling." (PMID 38849574, 2024). "Unexpectedly, these mice developed severe, lethal dermatitis and systemic inflammation indistinguishable in timing and severity from Casp8E-KO mice, underscoring that ZBP1 loss alone was insufficient to delay disease onset, progressions and severity." (PMID 40834903, 2025). "We therefore hypothesized that ZBP1 might drive TNFR1-independent skin inflammation in FADDE-KO mice." (PMID 38849574, 2024). "Mice with epidermal keratinocyte-specific ablation of RIPK1 (RIPK1E-KO) develop severe skin inflammation mediated by RIPK3-MLKL-dependent keratinocyte necroptosis, which is strongly suppressed by ZBP1 deficiency but only partially ameliorated by TNFR1 knockout." (PMID 38849574, 2024). "Moreover, our results provide experimental evidence that ZBP1 induces skin inflammation exclusively by triggering cell death arguing against a role of ZBP1 in inducing cell death-independent inflammatory signaling." (PMID 38849574, 2024). "Collectively, these results showed that ZBP1 and TNFR1 cooperate to induce keratinocyte necroptosis and skin inflammation in FADDE-KO mice." (PMID 38849574, 2024). "Absence of the RIPK1 RHIM domain in KCs leads to spontaneous Z-DNA-binding protein 1 (ZBP1)-dependent necroptosis, severe skin inflammation and perinatal lethality." (PMID 38649745, 2024). "Here we identified a critical interplay between RIPK3-MLKL-dependent necroptosis and FADD-caspase-8-mediated apoptosis that controls skin inflammation downstream of TNFR1 and ZBP1." (PMID 38849574, 2024). "Neither TNFR1 deficiency nor ZBP1 ablation alone was sufficient to inhibit skin inflammation; however, the double deficiency of ZBP1 and TNFR1 prevented skin inflammation." (PMID 40006996, 2025). "Constitutive absence of ZBP1 completely rescued the lethal dermatitis observed in Casp8E-KOTnfr1−/− mice through adulthood." (PMID 40834903, 2025). "However, because inhibition of FADD/caspase-8 signaling in keratinocytes triggers TNFR1- and ZBP1-mediated necroptosis and skin inflammation, it is not possible to use conditional ablation of FADD or caspase-8 alone to assess the role of FADD/Caspase-8-induced signaling in ZBP1caE-het mice." (PMID 38849574, 2024). "Notably, ZBP1 ablation on its own was not sufficient to inhibit skin inflammation in FADDE-KO mice." (PMID 38849574, 2024).
skin inflammation (continued). "Our previous studies identified ZBP1 as a potent driver of keratinocyte necroptosis and skin inflammation in mice lacking RIPK1 in keratinocytes or expressing RIPK1 with mutated RHIM, suggesting that ZBP1 could be implicated in inducing keratinocyte necroptosis in FADDE-KO mice." (PMID 38849574, 2024).
ZIKV infection (4 papers, 2019 to 2022). "One recent study published while this manuscript was in preparation suggests that ZBP1 senses ZIKV infection and restricts disease pathogenesis after intracranial inoculation of ZIKV in mice." (PMID 31572318, 2019). "We previously reported that WNV and ZIKV infections induce dramatic up-regulation of ZBP1 in mouse brains as well as in infected primary mouse cells." (PMID 31572318, 2019). "In the present study, we show the critical role of ZBP1 in restricting the pathogenesis of WNV and ZIKV infections." (PMID 31572318, 2019). "Herein, we show the critical role of ZBP1 in restricting the pathogenesis of WNV and ZIKV infections." (PMID 31572318, 2019). "There is need for further mechanistic studies to understand how ZBP1 restricts peripheral WNV and ZIKV infection." (PMID 31572318, 2019).
acute respiratory distress syndrome (3 papers, 2020 to 2025). Progressive and life-threatening pulmonary distress in the absence of an underlying pulmonary condition, usually following major trauma or surgery. "A previous study indicated that ZBP1 is abnormally expressed in H1N1-induced pneumonia associated with acute respiratory distress syndrome in mice." (PMID 32969837, 2020).
asthma (3 papers, 2023 to 2025). "The pathological relevance of ZBP1-mediated PANoptosis is well documented across multiple diseases, including asthma, acute myeloid leukemia, ultraviolet radiation-induced skin damage, tumorigenesis, and spinal cord injury." (PMID 40995563, 2025). "Here, we found that deficiency of PTRF could reduce lung IL-33, ZBP1, phosphor-receptor-interacting protein kinase 3 (p-RIPK3), and phosphor-mixed lineage kinase domain-like (p-MLKL) (necroptosis executioner), and airway inflammation in an HDM-induced asthma mouse model." (PMID 37454215, 2023). "Human epithelial cells from patients with asthma stimulated in vitro with RV‐A16 showed an upregulation of genes involved in DNA‐sensing and STING pathway such as the DNA sensors ZBP1, IFI16 and the cytosolic TRIM21." (PMID 39466641, 2025).
autoimmune disease (3 papers, 2023 to 2025). A disorder resulting from loss of function or tissue destruction of an organ or multiple organs, arising from humoral or cellular immune responses of the individual to their own tissue constituents. "The redundancy and overlap in multiple receptors and their signaling pathways, such as those seen in the roles of PKR, ZBP1, and MDA5 in the lethality associated with ADAR1 deficiency, could render single-target interventions ineffective, particularly in autoimmune diseases." (PMID 39143032, 2024).
ileitis (3 papers, 2024). "Ablation of ZBP1 or TNFR1 alone could not inhibit ileitis in FADDIEC-KO mice, however, combined ablation of both ZBP1 and TNFR1 strongly suppressed the pathology revealing a functional redundancy between these two proteins." (PMID 38849574, 2024).
ovarian carcinoma (3 papers, 2022 to 2024). A malignant neoplasm originating from the surface ovarian epithelium. "On the other hand, inhibition of ZBP1 expression might increase the migration of ovarian cancer, and impair fisetin-induced apoptosis." (PMID 38684755, 2024). "However, there is still a lack of evidence for how ZBP1 regulates cell death in ovarian cancer." (PMID 35538559, 2022).
parasitic infection (3 papers, 2021 to 2025). "ZBP1 as a PRR that induces immunity could fit within the realm of bacterial and parasitic infection (23, 49, –, 51)." (PMID 33526566, 2021).
Yersinia infection (3 papers, 2021 to 2025). "Previously, ZBP1-mediated PANoptosis has been proven to play a vital role in many infectious diseases by promoting cell death and inflammation to activate host defense or inflammatory tissue damage, such as C. albicans, A. fumigatus, SARS-CoV-2, influenza A virus and Yersinia infections." (PMID 39863598, 2025). "In further support of the importance of the TRIFosome in Yersinia infection, cleavage of CASP8 was inhibited nearly entirely in the absence of TRIF, and partially in the absence of ZBP1 and RIPK1 kinase activity in the context of high MOI Yersinia infection." (PMID 33397971, 2021).
Alzheimer disease (2 papers, 2024 to 2025). A progressive, neurodegenerative disease characterized by loss of function and death of nerve cells in several areas of the brain leading to loss of cognitive function such as memory and language. "Moreover, aberrant microglia activation and synaptic pruning is observed in neurodegenerative diseases such as Alzheimer’s disease, and ZBP1 also controls the NRLP3 inflammasome, a key regulator of neuroinflammatory phenotypes in Alzheimer’s disease." (PMID 38528182, 2024).
Autoimmunity (2 papers, 2023 to 2024). The occurrence of an immune reaction against the organism's own cells or tissues. "Taken together, the interactions of ADAR1 with the MDA5, PKR, and ZBP1 dsRNA-sensing pathways demonstrate how ADAR1 utilizes its versatile domain architecture to safeguard the cell from dsRNA autoimmunity on multiple fronts." (PMID 39682701, 2024).